SMAD4 (SMAD family member 4)
Diseases named in the same sentence as SMAD4 in open-access papers (continued):
Sharing a sentence is not in itself a finding about the gene and the disease.
prostate carcinoma (continued). "MiR-539 acts as a tumor suppressor in prostate cancer by down-regulating Distal-less 1 through the TGF-β/Smad4 signaling pathway." (PMID 40004485, 2025). "In another study, it has been reported that genistein increases the expression of tumor suppressors sFRP1 and Smad4 in prostate cancer cells by reducing the expression of miR-1260b and also DNA methylation." (PMID 40718456, 2025). "miR1260b is reported to regulate two tumor suppressor genes, sFRP1 and SMAD4, in prostate cancer through epigenetic mechanisms, and to also extensively participate in arthritis, osteogenic differentiation, and Alzheimer's disease." (PMID 38658973, 2024). "According to the previous findings, both of these miRNAs (miR-182 and miR-183) down-regulate the SMAD4 expression in human bladder, prostate cancer, and ovarian cancer." (PMID 35399004, 2022). "For instance, overexpression of oncomiR-1260b resulted in reduced levels of tumor suppressor SMAD4 leading to prostate cancer progression." (PMID 36091792, 2022). "SENP1 also promotes EMT of prostate cancer cells via regulating SMAD4 de-SUMOylation and it regulates PTEN stability to promote prostate cancer development." (PMID 33572160, 2021). "SPP1 participates in the recurrence and metastasis of prostate cancer by mediating the BP of the Smad4/PTEN pathway." (PMID 33954053, 2021). "miR-19a-3p, which targets the downstream effectors of TGFβ signaling, SMAD2, and SMAD4, is known to inhibit prostate cancer cell invasion and migration." (PMID 34503200, 2021). "In prostate cancer cells, the expression of sFRP1 and Smad4 are down-regulated by increased expression of miR-1260b, resulting in cell proliferation, invasion, migration and TCF reporter activity." (PMID 34289845, 2021). "Silencing of miR-1260b in prostate cancer cells enhanced the expression of sFRP1 and Smad4 and decreased cellular proliferation, invasion, and migration." (PMID 32523124, 2020). "miR-301a represses the expression of SMAD4, promoting the proliferation of prostate cancer cells in vitro and tumor growth in vivo." (PMID 31842336, 2019). "In conclusion, SENP1 deSUMOylated SMAD4 to promote EMT via up-regulating E-cadherin in prostate cancer cells." (PMID 28417919, 2017). "Up-regulation of SENP1 promotes deSUMOylation of SMAD4 in prostate cancer cells, which reduces the SMAD4 levels and impairs TGF-β/SMADs-mediated transcription activities." (PMID 28417919, 2017). "Among the SMADs, SMAD4 is an important tumor suppressor, which has also been recognized as a potential molecular maker for diagnosis of prostate cancer." (PMID 28417919, 2017). "BMP-9 has also been shown to activate the ALK2/Smad1/Smad4 and the ALK4/Smad1 pathways to promote ovarian cancer cell proliferation and to cause apoptosis in prostate cancer cells." (PMID 27650540, 2016). "SMAD4 was down-regulated in our TCGA prostate cancer data and has also been found to be down-regulated in prostate cancers, including advanced tumors." (PMID 26683658, 2015). "SMAD4, a critical component of the TGF-β signaling cascade, is inactivated in a subset of advanced prostate cancers through promoter hypermethylation or somatic mutation, and its expression is reduced in metastatic prostate cancer." (PMID 25749039, 2015). "Consistently, the prostate-specific PTEN and Smad4 double knock-out results in the development of prostate cancer with metastasis." (PMID 25295225, 2014). "Another key regulator that was investigated in prostate cancer is SMAD4, which is a putative suppressor of prostate tumor progression." (PMID 24391925, 2013).
prostate carcinoma (continued). "Interestingly, miR-1260b was also significantly downregulated by another natural polyphenol known for its anticancer properties, i.e. genistein that promoted SMAD4-mediated apoptosis in prostate cancer cells." (PMID 36091792, 2022). "They further demonstrated that SIRT7 expression is positively correlated with AR signaling in both prostate cancer tissues and cells (LNCaP and 22Rv1) and that SIRT7 knockdown upregulates SMAD4, a tumor suppressor protein, which interacts with AR to control its signaling in prostate cancer." (PMID 36291902, 2022). "Given the variety of tumor suppressor genes and oncogenes manipulated to model prostate cancer using the PB-Cre4 driver, it is remarkable that concurrent inactivation of Smad4 and Apc were the only reported genetic changes sufficient to drive oncogenesis of mouse penile epithelium." (PMID 32358507, 2020). "In this model, enhanced activation of the PI3K pathway and increased levels of Smad4 protein were observed, whereas reduced Smad4 expression correlated with metastatic tumor progression, supporting a role of Smad4 acting as a tumor suppressor in prostate cancer." (PMID 32888405, 2020). "Smad4 or DPC4 belongs to a family of signal transduction proteins, and inactivation and somatic mutations of Smad4 are often found in pancreatic, colorectal, and prostate cancers." (PMID 33322272, 2020). "Similarly in a PTEN-null mouse model, genetic depletion of Smad4 resulted in emergence of more invasive and metastatic prostate cancer when compared to tumors from normal PTEN-null animals that possessed enhanced TGFβ/BMP-Smad4 pathway activation." (PMID 32585812, 2020). "Likewise, a recent study showed that the overexpression of miR-888 increased cellular proliferation and migration by targeting the tumor suppressor genes RBL1 and SMAD4, suggesting the oncogenic role of miR-888 in prostate cancer progression." (PMID 33123477, 2020). "Osteopontin dysregulation in prostate cancer may cooperate with PTEN and SMAD4 loss to contribute to aggressive and metastatic prostate cancer in transgenic models." (PMID 31136607, 2019). "The combination of PTEN/SMAD4 does not predict risk for prostate cancer recurrence, but the PTEN/SMAD4/CCND1/SPP1 four-gene signature does." (PMID 31551414, 2019). "Additionally, several direct targets of miR-183 have also been proposed, such as ezrin in lung cancer cells, together with Dkk-3 and SMAD4 in prostate cancer cells." (PMID 31210063, 2019). "Oncogenic microRNA miR-1260b targets both Smad4 and secreted frizzled-related protein 1 (sFRP1, an endogenous Wnt pathway inhibitor), suggesting that there is a population of prostate cancer patients in which the Wnt pathway is up-regulated while the BMP and TGFβ pathways are inactivated." (PMID 29113300, 2017). "To test if SENP1 could deSUMOylate SMAD4 in prostate cancer cells, we analyzed SMAD4 expression in PC3M cells after infection with PLKO.1-shSENP1 or PLKO.1-shScramble." (PMID 28417919, 2017). "Smad4 is deleted in approximately 10% of prostate cancer cases." (PMID 29113300, 2017). "It has been reported that down-regulation or inactivation of SMAD4 could promote the development and progression of prostate cancer, and SMAD4 has been emerged as a potential biomarker for diagnosis." (PMID 28417919, 2017). "Therefore, we propose that SENP1 up-regulation in prostate cancer cells deSUMOylates SMAD4, which in turn regulates E-cadherin, induces EMT of tumor cells and promotes tumor metastasis." (PMID 28417919, 2017). "Taken together, these studies suggest that SENP1 silencing could inhibit the EMT of prostate cancer cells via up-regulating SMAD4 expression." (PMID 28417919, 2017). "Furthermore, knockdown of Smad4 significantly increased E-cadherin expression in prostate cancer cells." (PMID 26817584, 2016). "TGF-β1 inhibits the growth of PC3 (a prostate cancer cell line with wild-type Smad4) by decreasing the membrane-associated PKCα, not by altering the total level of PKCα." (PMID 20684793, 2010).
prostate carcinoma (continued). "Therefore, we investigated if SENP1 deSUMOylated SMAD4 in prostate cancer cells." (PMID 28417919, 2017). "However, the role of SENP1 in regulating deSUMOylation of SMAD4 in prostate cancer is largely unknown." (PMID 28417919, 2017). "Knockout of Smad4, a key component of the TGF-β pathway, results in invasive, metastatic, and lethal prostate cancers with 100% penetrance." (PMID 38781024, 2024). "SMAD4 provides a barrier to metastatic progression in PTEN-null mouse prostates, and when deleted, it drives highly aggressive prostate cancer that metastasizes to the lymph node and lung." (PMID 38751776, 2024). "A previous study discovered that Inmt overexpression in prostate cancer cells inhibited effectors of Wnt and TGF-β pathways, including SMAD4." (PMID 38391940, 2024). "In prostate cancer, miR-582-5p can inhibit tumor metastasis by targeting several components of TGF-β signaling, including SMAD2, SMAD4, TGFBRI, and TGFBRII." (PMID 34978519, 2021). "The latest study validated RBL1, KLF5, SMAD4, and TIMP2 as the direct miR-888 targets in prostate cancer." (PMID 33123477, 2020). "SMAD4 is a key regulator of the TGFβ pathway and a suppressor of prostate tumor progression, whereas cyclin D1 and SPP1 act as mediators of the prostate cancer processes." (PMID 31551414, 2019). "Specifically, a miR-331-3p-induced decrease of NRP2 and NACC1 results in upregulations of TGF-β1 and SMAD4, triggering EMT of prostate cancer cells." (PMID 31842336, 2019). "Given that we found SIRT7 destabilized SMAD4, it indirectly supports the notion that higher expression of SIRT7 promoted prostate cancer metastasis." (PMID 28827661, 2017). "Expression analysis of the TGF-β and BMP pathways (that both converge on SMAD4) revealed significantly reduced expression of TGF-β and BMP ligands in both untreated and castration resistant prostate cancer." (PMID 25749039, 2015). "A previous study has shown that combined deletion of SMAD4 and PTEN in mouse prostates leads to aggressive prostate cancer with 100% penetrance." (PMID 25749039, 2015). "Using this approach, we confirm that four previously reported prognostic markers, PTEN, SMAD4, CCND1 and SPP1, can predict lethal outcome of human prostate cancer." (PMID 25075204, 2014). "Additionally, PELO promotes prostate cancer progression by enhancing PLK1-induced ubiquitination and degradation of Smad4." (PMID 40764425, 2025). "Inactivation of PTEN and SMAD4 and activation of cyclin D1 and SPP1 promote prostate cancer." (PMID 31551414, 2019). "However, deletion of SMAD4 in addition to PTEN invariably resulted into the development of metastatic, lethal prostate cancer at an early age, whereas SMAD4 ablation on its own reportedly did not cause any prostatic lesions." (PMID 31160676, 2019). "These mice model non-metastatic castration resistant prostate cancer and should provide novel information for tumors that have genetic aberrations in the Wnt pathway or Smad4." (PMID 29113300, 2017). "Several reports have shown that SUMOylation could improve the stability and enhance the expression levels of SMAD4, which not only increases TGF-β-mediated transcription, but also negatively regulates ARs in prostate cancer." (PMID 28417919, 2017).
prostate carcinoma (continued). "Furthermore, miR224 binds to the Smad4 and Homeobox D10 (HOXD10) to promote migration of HCC and CRC while it binds to the TPD52 to inhibit migration of prostatic cancer PCa cells." (PMID 27323393, 2016). "Furthermore, DACH1 binds Smad4 and NCoR to repress TGF-β signaling, enhances chemosensitivity by inducing the expression of P21, and regulates hormone levels in breast and prostate cancers." (PMID 30261897, 2018).
hereditary hemorrhagic telangiectasia (75 papers, 2008 to 2026). A disorder of angiogenesis leading to arteriovenous dilatations: cutaneo-mucosal hemorrhagic telangiectasias and visceral shunting. "People with SMAD4 mutations have an increased likelihood of developing hereditary hemorrhagic telangiectasia (HHT)." (PMID 39195204, 2024). "Genetically related allelic disorders of SMAD4 also have variants in this region, including hereditary haemorrhagic telangiectasia (HHT) alongside SMAD4 + JPS, and Myhre syndrome, independent of JPS." (PMID 38066625, 2023). "The patient with the SMAD4 pathogenic variant was evaluated for hereditary hemorrhagic telangiectasia (HHT) and commenced upper gastrointestinal (GI) surveillance in addition to lower GI surveillance." (PMID 35128723, 2022). "All publications from the ACVRL1, ENG and SMAD4 Mutation Databases and publications searched for terms “hereditary hemorrhagic telangiectasia” and “founder” in PubMed and Scopus, respectively, were extracted." (PMID 33919892, 2021). "We characterized the NK cell phenotype and function in three family members with Hereditary Hemorrhagic Telangiectasia (HHT) due to heterozygous SMAD4 mutations." (PMID 31118932, 2019). "Due to the association between SMAD4 mutations and hereditary haemorrhagic telangiectasia, the patient was referred to echocardiography and ultrasound of the liver." (PMID 25705527, 2015). "Patients with SMAD4 mutations should be screened for hereditary hemorrhagic telangiectasia, (HHT) symptoms, in particular the presence of pulmonary AV-malformations." (PMID 25022750, 2014). "Interestingly, mutations in GDF2, as well as in ACVRL1, ENG and SMAD4 are also known to be causal of hereditary haemorrhagic telangiectasia (HHT)." (PMID 41222740, 2025). "A subgroup of patients with JPS and a PV in SMAD4 may have symptoms of hereditary hemorrhagic telangiectasia (HHT) as well as an increased risk of aortic aneurisms." (PMID 34620187, 2021). "JPS patients with SMAD4 mutations predominantly exhibit upper gastrointestinal polyps and hereditary hemorrhagic telangiectasia (HHT), while BMPR1A-mutated patients mainly present with colonic phenotypes." (PMID 40226309, 2025). "Additionally, most individuals with pathogenic variants in SMAD4 have hereditary hemorrhagic telangiectasia (HHT) (MIM: 175050)." (PMID 41250769, 2025). "Mutations in ALK1 result in type 2 hereditary hemorrhagic telangiectasia; mutations in ENG and SMAD4 result in vascular malformation." (PMID 39022219, 2024). "Because patients with pathogenic SMAD4 variants commonly have one or more features of hereditary hemorrhagic telangiectasia (HHT), these patients may potentially increase their risk for developing severe aortic symptoms when taking fluoroquinolones." (PMID 35685436, 2022). "A subset of patients with JPS also has hereditary hemorrhagic telangiectasia (HHT), more commonly seen in SMAD4 mutation carriers and characterized by mucocutaneous telangiectasias, gastrointestinal arteriovenous malformations and pulmonary arterio-venous malformations." (PMID 33806975, 2021). "Hereditary hemorrhagic telangiectasia (HHT), a rare autosomal dominant disease mostly caused by mutations in three known genes (ENG, ACVRL1, and SMAD4), is characterized by the development of vascular malformations (VMs)." (PMID 32842615, 2020). "Arteriovenous malformations are very frequent in patients who suffer from Hereditary Hemorrhagic Telangiectasia (HHT), a disease associated with reduced ALK1, ENG, or SMAD4 function." (PMID 29230182, 2017). "Mutations in Alk1, its co-receptor endoglin or the common effector Smad4 are involved in the pathogenesis of hereditary hemorrhagic telangiectasia (HHT), a vascular condition characterized by arteriovenous malformations (AVM)." (PMID 27517154, 2016).
hereditary hemorrhagic telangiectasia (continued). "Some of the patients with SMAD4 mutations present with another autosomal dominant syndrome, hereditary hemorrhagic telangiectasia (HHT) in which bleeding from arteriovenous malformations (AVMs) may occur." (PMID 24760231, 2014). "However, in anaemic patients and in cases of SMAD4 variants, SBCE is proposed for evaluation of Hereditary Haemorrhagic Telangiectasia (HHT) overlap syndrome." (PMID 41226105, 2025). "Conversely, mutation of the BMP receptors activin-like kinase 1 (ALK1), endoglin (ENG), or the downstream effector, SMAD family member 4 (SMAD4) leads to hereditary hemorrhagic telangiectasia (HHT), characterized by fragile and leaky arterial-venous malformations (AVMs)." (PMID 37490341, 2023). "The endogolin (ENG)g (*131195), activin A receptor type 1 (AVCRL1) (*601284), SMAD4 (SMAD family member 4) (*600993), and growth differentiation factor 2 (GDF2) (*605120) genes have been identified as the underlying cause of hereditary hemorrhagic telangiectasia." (PMID 31594285, 2019). "Hereditary hemorrhagic telangiectasia (HHT) is a potentially life-threatening genetic vascular disorder caused by loss-of-function mutations in the genes encoding activin receptor-like kinase 1 (ALK1), endoglin, Smad4, and bone morphogenetic protein 9 (BMP9)." (PMID 27874028, 2016). "Patients with a SMAD4 mutation should be followed up both for JPS and haemorrhagic hereditary telangiectasia and may develop protein loosing enteropathy and immunodeficiency." (PMID 25705527, 2015). "Hereditary hemorrhagic telangiectasia (HHT), which is caused by pathogenic variants in genes such as ENG (endoglin), ACVRL1 (ALK1), and less commonly SMAD4, is one such condition that predisposes individuals to multiple AVMs." (PMID 41555917, 2025). "The most frequently associated genetic mutations involve the hereditary hemorrhagic telangiectasia (HHT) genes (ENG, ACVRL and SMAD4) and RASA1 -- which are also implicated in brain AVM and VOGM, respectively." (PMID 38506930, 2024). "In hereditary hemorrhagic telangiectasia (HHT), mutations in ENG or ACVRL1 are frequently observed, while SMAD4 mutations affect a small percentage of patients." (PMID 38673717, 2024). "Mice lacking ALK1, its co-receptor endoglin, or the common effector SMAD4, are involved in the pathogenesis of hereditary hemorrhagic telangiectasia (HHT), characterized by the presence of telangiectasias and arteriovenous malformations." (PMID 35954181, 2022). "SMAD4-JPS phenotypes include hereditary hemorrhagic telangiectasia (HHT), a vascular dysplasia affecting 76% of carriers." (PMID 35158896, 2022). "In addition, a mutation of the SMAD4 gene on chromosome 18 (tumor suppressor gene that mediates TGF-beta) is associated with a combination syndrome involving both juvenile polyposis and hereditary hemorrhagic telangiectasia, seen in approximately 1–2% of tested patients." (PMID 34882285, 2021). "Hereditary hemorrhagic telangiectasia (HHT) is an autosomal dominant vascular disorder caused by mutations in ENG, ACVRL1 and SMAD4, which function in regulating the transforming growth factor beta and bone morphogenetic protein signaling pathways." (PMID 27081547, 2015). "These entities are often sporadic but are found in association with variants of the RASA1 and EPHB4 genes (capillary malformation–arteriovenous malformation, CMAVM; OMIM #608354) or ACVRL1, ENG, and SMAD4 genes (hereditary hemorrhagic telangiectasia, HHT; OMIM #187300)." (PMID 40259928, 2025). "Hereditary hemorrhagic telangiectasia (HHT), a genetic disorder may be caused by mutations in genes such as ENG (encoding endoglin) or ACVRL1 (ALK1), and less commonly SMAD4, is one condition that predisposes individuals to multiple AVMs." (PMID 41555917, 2025).